CDCA7 (cell division cycle associated 7)
Diseases named in the same sentence as CDCA7 in open-access papers (continued):
Sharing a sentence is not in itself a finding about the gene and the disease.
glioma (4 papers, 2021 to 2025). A benign or malignant brain and spinal cord tumor that arises from glial cells (astrocytes, oligodendrocytes, ependymal cells). "To further investigate the mechanisms underlying the role of CDCA7 in glioma, we conducted a GSEA study to find the possible mechanisms and signaling pathways associated with the enhancement of CDCA7 in glioma." (PMID 37510310, 2023). "We found that the increase in CDCA7 level positively correlated with a rise in the diagnostic grade of gliomas." (PMID 37510310, 2023). "Taken together, these findings demonstrated that increased CDCA7 expression is significantly associated with the increased malignancy of glioma." (PMID 37510310, 2023). "The expression level of CDCA7 in glioma is positively correlated to disease grade, IDH mutation status, and 1p/19q codeletion." (PMID 37510310, 2023). "The association between CDCA7 and these tumor immune checkpoint molecules suggests that CDCA7 can also be used as a valuable biomarker for predicting prognosis and an immunotherapy target for glioma." (PMID 37510310, 2023). "The CDCA family was specifically expressed in malignant glioma cells, while CDCA7 is specifically expressed in NPC-like malignant cells." (PMID 38181024, 2024). "Compared with normal tissues, CDCA7 expression was significantly up-regulated in glioma tissues after analysis of data obtained from both the TCGA and CGGA databases." (PMID 37510310, 2023). "Subsequently, we compared the expression levels of CDCA7 in gliomas bearing a wild-type or mutant IDH and found that CDCA7 was highly enriched in gliomas carrying a wild-type IDH." (PMID 37510310, 2023). "CDCA7 expression level data were obtained from the Chinese Glioma Genome Atlas (CGGA) and The Cancer Genome Atlas (TCGA) databases, and the enriched genes and related signaling pathways were explored." (PMID 37510310, 2023). "CDCA7 can be a new prognostic factor for glioma, which is closely related to ferroptosis, tumor immune cell infiltration, and immune checkpoint." (PMID 37510310, 2023). "To further study the relationship between CDCA7 and the immune microenvironment of glioma tissues, we conducted a more accurate analysis and revealed the relationship between CDCA7 and the immune checkpoint molecules in glioma." (PMID 37510310, 2023). "Meanwhile, the high expression of CDCA7 was closely related to several clinicopathological parameters of glioma patients." (PMID 37510310, 2023). "The increased expression of CDCA7 in glioma promoted our analysis of the relationship between CDCA7 levels and the survival of glioma patients." (PMID 37510310, 2023). "In conclusion, our study revealed an elevated expression of CDCA7 in gliomas and investigated the biological functions of CDCA7." (PMID 37510310, 2023). "We then studied the relationship between CDCA7 level and clinicopathologic parameters of glioma patients." (PMID 37510310, 2023). "According to the expression level of CDCA7, glioma patients were divided into low-expression and high-expression groups." (PMID 37510310, 2023). "To further explore the potential effect of CDCA7 on the infiltration of 22 kinds of tumor immune cells in gliomas, we divided the samples into two groups (high and low) based on expression of CDCA7." (PMID 37510310, 2023). "Specifically, analysis of data from the TCGA database showed that the higher expression level of CDCA7 indicates a lower survival rate and poorer prognosis in glioma patients." (PMID 37510310, 2023). "Several pathways exhibiting significant differential enrichment in gliomas correlated with high CDCA7 expression phenotypes were identified using the data from the CGGA and TCGA databases based on NES and FDR q-values (FDR < 0.05), respectively." (PMID 37510310, 2023).
glioma (continued). "This expounded a potential mechanism of CDCA7 in regulating the proliferative ability of glioma." (PMID 38181024, 2024). "In addition, we also revealed the potential role of CDCA7 in regulating ferroptosis by interacting with several ferroptosis suppressor genes in gliomas and identified potential targets of CDCA7 in gliomas through PPI analysis." (PMID 37510310, 2023). "CDCA7 was significantly increased in gliomas in comparison to healthy tissues." (PMID 37510310, 2023). "Systemic analysis of the biological functions and signaling pathways of CDCA7 in gliomas may improve our understanding of the molecular mechanism of this molecule in affecting the occurrence or progression of glioma." (PMID 37510310, 2023). "The expression of CDCA7 is a significant indicator of the poor prognosis of glioma patients." (PMID 37510310, 2023). "We found that gliomas exhibited higher expression of CDCA7 than normal tissues." (PMID 37510310, 2023). "In addition, we divided glioma patients into two groups based on the expression level of CDCA7—a low-expression group and a high-expression group—for survival analysis." (PMID 37510310, 2023). "The increase in CDCA7 was positively correlated with multiple ferroptosis suppressor genes and genes involved in tumor-infiltrating immune cells and immune checkpoint molecules in glioma." (PMID 37510310, 2023). "Further research also found that the expression level of CDCA7 correlates with tumor infiltration of immune cells and the expression of immune checkpoint molecules, which may indicate a role for CDCA7 as a new immunotherapeutic target in treating gliomas." (PMID 37510310, 2023). "Considering the critical role of ferroptosis in the development of glioma and the undefined role of CDCA7 in regulating ferroptosis we reasoned that CDCA7 may regulate ferroptosis via these signaling pathways." (PMID 37510310, 2023). "Furthermore, Gene Ontology (GO), gene set enrichment analysis (GSEA), and Kyoto Encyclopedia of Genes and Genomes (KEGG) analysis revealed the biological function of CDCA7 in glioma and its related enriched genes and pathways." (PMID 37510310, 2023). "In addition, the potential role of CDCA7 in ferroptosis and its effects on glioma need to be confirmed in both in vitro and in vivo experiments." (PMID 37510310, 2023). "Therefore, our study shows that CDCA7 is closely related to the infiltration of multiple immune cells involved in cancer progression, and thus provides further evidence for the prognostic role of glioma." (PMID 37510310, 2023). "Therefore, CDCA7 may be a promising prognostic biomarker and a target for the clinical treatment of glioma." (PMID 37510310, 2023). "Moreover, with the increase in glioma grading, the expression of CDCA7 also increased." (PMID 37510310, 2023). "However, the clinical relevance and potential mechanisms of CDCA7 in glioma are unclear." (PMID 37510310, 2023). "Finally, the molecular mechanism by which CDCA7 regulates the progression of glioma is unclear." (PMID 37510310, 2023). "Combined with the GDSC drug database, CDCA2, CDCA4, CDCA5, CDCA7, and CDCA8 have potential as clinical drug treatments for glioma." (PMID 38181024, 2024). "CDCA2, CDCA4, CDCA5, CDCA7, and CDCA8 showed high accuracy for diagnosing gliomas, with CDCA7 having the highest accuracy (AUC: 0.982)." (PMID 38181024, 2024).
glioma (continued). "Glioma single-cell atlas reveals specific expression of CDCA3, 4, 5, 8 in malignant cells and CDCA7 in neural progenitor cells (NPC)-like malignant cells." (PMID 38181024, 2024). "To investigate the differential expression of CDCA7 in normal brain tissues and gliomas, we retrieved glioma RNA sequencing datasets from the TCGA and CGGA databases and obtained the expression of CDCA7 in normal tissues from the GTEx database." (PMID 37510310, 2023). "In the present study, we analyzed the expression of CDCA7 in the TCGA, CGGA, and GTEx databases and found that the expression of CDCA7 in glioma was up-regulated compared with normal tissues." (PMID 37510310, 2023). "Through analysis of glioma samples in the CGGA and TCGA databases, we found that CDCA7 expression level was significantly correlated with tumor-related immunosuppressive molecules, including CD80, CD276, CD28, PDCD1LG2, and TNFSF4." (PMID 37510310, 2023). "CDCA2, CDCA3, CDCA4, CDCA5, CDCA7, and CDCA8 were significantly highly expressed in glioma samples." (PMID 38181024, 2024). "To date, no study is available to elucidate the role of CDCA7 in ferroptosis and its effect on the occurrence and progression of gliomas." (PMID 37510310, 2023). "In this study, we conducted a comprehensive and systematic bioinformatics analysis of RNA sequencing data retrieved from the Chinese Glioma Genome Atlas (CGGA) and The Cancer Genome Atlas (TCGA) databases and found that the expression of CDCA7 in gliomas was much higher than that in normal tissues." (PMID 37510310, 2023). "Finally, our analysis revealed that CDCA7 expression levels in gliomas without 1p/19q coding were higher than those in 1p/19q coding samples." (PMID 37510310, 2023). "However, so far, there is no detailed study on the role of CDCA7 in glioma." (PMID 37510310, 2023). "According to other reports, CDCA7 could enhance the activation of TGF-β and thereby promote ferroptosis of hepatocellular carcinoma cells by repressing the expression of SLC7A11 and enhancing lipid peroxidation, which is inconsistent with our inference that CDCA7 inhibits ferroptosis in gliomas." (PMID 37510310, 2023). "Further analysis showed that the expression of CDCA7 was positively correlated with tumor grade, wild-type IDH, and 1p/19q non-codeletion in glioma." (PMID 37510310, 2023). "As an MYC target gene, JPO1/CDCA7 is also frequently over-expressed in human cancers, but its expression in gliomas has not been studied." (PMID 37510310, 2023).
ovarian carcinoma (4 papers, 2021 to 2025). A malignant neoplasm originating from the surface ovarian epithelium. "The purpose of the current study was to investigate the biological function of cell division cycle-associated protein 7 (CDCA7) on ovarian cancer (OC) progression and analyze the molecular mechanism of CDCA7 on OC cellular processes and angiogenesis." (PMID 34551671, 2021). "CDCA7 promotes tumor cell proliferation, invasion, and metastasis in various cancers, including esophageal, gastric, and ovarian cancers, and regulates malignant biological processes, including inflammatory factors." (PMID 39905019, 2025). "In summary, circASH1L acts as a sponge for miR-515-5p and regulates the expression of CDCA7 in ovarian cancer cells." (PMID 40630134, 2025). "UALCAN analysis revealed that low CDCA7 expression was correlated with low tumor grade, while the expression of CDCA7 progressively increased from stage 2 to stage 3 in ovarian cancer samples." (PMID 40630134, 2025). "The clinical relevance of circASH1L/miR-515-5p/CDCA7 axis in ovarian cancer patients was analyzed using public datasets." (PMID 40630134, 2025). "Compared with that in NOEC cells, CDCA7 protein and mRNA levels in ovarian cancer cells (OVCAR3, SKOV3, CAOV-3, A2780) were distinctly upregulated, especially in SKOV3 cells." (PMID 34551671, 2021). "Targeting the circASH1L/miR-515-5p/CDCA7 pathway offers new insights into the relationship between ferroptosis and chemoresistance, presenting a promising strategy to overcome chemoresistance in ovarian cancer." (PMID 40630134, 2025). "While CDCA7 knockdown arrests cell cycle and inhibits cell proliferation in ovarian cancer." (PMID 40630134, 2025). "The starBase database analysis showed a positive correlation between CDCA7 and RRM2 expression in ovarian cancer (p < 0.01)." (PMID 40630134, 2025). "TCGA data from the GEPIA database suggested that CDCA7 expression was significantly increased in ovarian cancer tissues compared to adjacent non-cancerous tissues (p < 0.05)." (PMID 40630134, 2025). "Moreover, differences of CDCA7 expression in normal ovarian epithelial cells (NOEC) and ovarian cancer cells (OVCAR3, SKOV3, CAOV-3, A2780) were assessed." (PMID 34551671, 2021).
pancreatic cancer (4 papers, 2022 to 2025). "Cell division cycle associated 7 (CDCA7) plays a role in various malignancies, especially pancreatic cancer (PC)." (PMID 39905019, 2025). "Similarly, cell division cycle-associated protein 7 (CDCA7) promotes glycolysis, facilitating pancreatic cancer cell proliferation and chemoresistance." (PMID 41441035, 2025).
chronic myelogenous leukemia (3 papers, 2013 to 2024). "Its counterpart, CDCA7, exhibits high expression during the blast crisis phase of chronic myelogenous leukemia, and transgenic mice overexpressing CDCA7 are at a significantly increased risk of developing lymphoid malignancies." (PMID 39796114, 2024).
esophageal squamous cell carcinoma (3 papers, 2021 to 2023). Esophageal squamous cell carcinoma (ESCC) is a type of esophageal carcinoma (EC) that can affect any part of the esophagus, but is usually located in the upper or middle third. "The role of CDCA7 in many cancers, such as clear cell renal cell carcinoma (ccRCC), esophageal squamous cell carcinoma (ESCC), colorectal cancer (CRC), and triple-negative breast cancer (TNBC), has been revealed in several previous reports." (PMID 37510310, 2023). "For instance, CDCA7 regulate the expression of CCNA2 to facilitate the tumor progression of Esophageal Squamous Cell Carcinoma." (PMID 36313774, 2022). "CDCA7 is a copy number amplified gene identified not only in esophageal squamous cell carcinoma (ESCC) but also in various cancer types." (PMID 34737951, 2021).
lymphoid tumors (3 papers, 2020 to 2024). "A recent study shows that CDCA7 is overexpressed in lymphoid tumors, and CDCA7 knockdown decreases the growth rate of the lymphoid tumor, without inhibiting the proliferation of normal cells." (PMID 32104702, 2020). "CDCA7 levels were also significantly elevated in a lot of T and B lymphoid tumor cell lines." (PMID 38333875, 2024). "Although CDCA7 is unnecessary for anchoring normal fibroblasts' dependent growth or non malignant lymphocytes, it is necessary but not adequate for anchoring independent growth of lymphoid tumors and lymphoid tumor cells." (PMID 38333875, 2024).
breast tumors (1 paper, 2013). "The expression levels and subcellular localization of the CCNB2, ASPM, CDCA7, KIAA0101, and SLC27A2 proteins were measured using immunohistochemistry (IHC) on a panel of 80 primary invasive breast tumors." (PMID 23282137, 2013).
diffuse large B-cell lymphoma (1 paper, 2025). "Cell division cycle-associated protein 7 (CDCA7) is a core target of MYC-dependent transcriptional regulation and is aberrantly overexpressed in MYC-rearranged diffuse large B cell lymphoma (DLBCL)." (PMID 41189944, 2025).
endometrial carcinoma (1 paper, 2020). A malignant tumor arising from the epithelium that lines the cavity of the uterine body. "When it comes to uterine mixed endometrial carcinoma, another distinctive pattern emerged and the most were the high mRNA expression of almost all CDCA members except CDCA3/7, and the missense mutation of NUF2, CDCA2/3/5, CBX2, CDCA7/8." (PMID 32913454, 2020).
esophageal cancer (1 paper, 2025). A primary or metastatic malignant neoplasm involving the esophagus. "CDCA7 promotes TGF-β-induced epithelial-mesenchymal transition to promote tumor progression by transcriptionally regulating Smad4/Smad7 in esophageal cancer cells." (PMID 39905019, 2025).
Esotropia (1 paper, 2024). A form of strabismus with one or both eyes turned inward ('crossed') to a relatively severe degree, usually defined as 10 diopters or more. "At the standard significance of p < 5 × 10−8, CDCA7 in chromosome 2 for esotropia, HLA-F in chromosome 6 for exotropia, and DAB1-AS1 in chromosome 1 for idiopathic superior oblique muscle palsy were suggested as candidates in a GWAS with BBJ (180K)." (PMID 39000095, 2024).
Hyperinsulinemia (1 paper, 2024). An increased concentration of insulin in the blood. "Additionally, hyperinsulinemia inhibited the transcriptome required for cell cohesion MELK, CDCA7, ESCO2, mitotic spindle assembly KIF15, SGO1, and AURKB, and kinetochore formation KNL and NDC80." (PMID 39768214, 2024).
leukemia (1 paper, 2024). A malignant (clonal) hematologic disorder, involving hematopoietic stem cells and characterized by the presence of primitive or atypical myeloid or lymphoid cells in the bone marrow and the blood. "Further, correlative analysis of using AML data from TARGET cohort revealed ARMH1 expression has a significant correlation with CDCA7 (r=0.29, P<2.2e-16) and c-MYC (r=0.2, P=4.6e-16) which suggests intersection between their regulatory pathways in leukemia cells." (PMID 39703843, 2024).
liver cancer (1 paper, 2023). An epithelial or non-epithelial malignant neoplasm that arises from the liver. "Further analysis showed that CDCA7 was positively associated with M0 macrophages and negatively associated with M2 macrophages, suggesting that CDCA7 could influence the progression of liver cancer cells by affecting macrophage polarization." (PMID 36860864, 2023). "Our findings suggested that CDCA7 could influence liver cancer cell progression by affecting macrophage polarization, providing a theoretical basis for liver cancer immunotherapy." (PMID 36860864, 2023). "Immunohistochemical results confirmed that the staining intensity of CDCA7 was prominently increased in the nucleus in primary liver cancer tissues compared to adjacent non-tumor tissues." (PMID 36860864, 2023). "Furthermore, our immunohistochemical results confirmed that the staining intensity of CDCA7 was prominently increased in the nucleus in primary liver cancer tissues compared to adjacent non-tumor tissues." (PMID 36860864, 2023).
multiple sclerosis (1 paper, 2017). A progressive autoimmune disorder affecting the central nervous system resulting in demyelination. "ZAK, a member of the MAP3K family, is known to be activated by stress and inflammation, while CDCA7 variants are associated with cell division and brain lesion formation in multiple sclerosis." (PMID 28569182, 2017). "Gene regions spanning the identified four-SNP signature, HLA-DQB2, MBP, UVRAG, and ZAK(CDCA7), are known to be related to either the MoA of Copaxone or the pathophysiology of multiple sclerosis: HLA-DQB2 is involved in antigen processing and presentation, central to Copaxone’s MoA." (PMID 28569182, 2017).
osteosarcoma (1 paper, 2020). A usually aggressive malignant bone-forming mesenchymal neoplasm, predominantly affecting adolescents and young adults. "Five of the seven immune-related genes (CDCA7, GZMA, SLC7A7, VAMP8, and EVI2B) were highly expressed in the osteosarcoma group, while two of these immune-related genes (IFITM3 and ACTA2) were lowly expressed." (PMID 33384961, 2020). "The heatmap of these seven immune-related genes expression level in GSE42352 indicated that five of these genes (CDCA7, GZMA, SLC7A7, VAMP8, and EVI2B) were highly expressed in the osteosarcoma group, but two of these genes (IFITM3 and ACTA2) were highly expressed in the normal group." (PMID 33384961, 2020).